ENSG00000253190 (novel transcript)
Gene: Long non-coding RNA gene on chromosome 8 (66,112,667 to 66,126,632, forward strand). Ensembl gene ENSG00000253190.
Gene Ontology:
Molecular function: triplet codon-amino acid adaptor activity
Biological process: translation